H19 (H19 imprinted maternally expressed transcript)
Diseases named in the same sentence as H19 in open-access papers (continued):
Sharing a sentence is not in itself a finding about the gene and the disease.
tumor (continued). "LncRNAs, including MALAT-1, HOTAIR, and H19, are commonly found in patients with BC because they affect key signaling pathways involved in tumor promotion and suppression." (PMID 35864503, 2022). "Considering the tumor-suppressive effect of miR-181a via downregulation of KRAS and the role of the KRAS mutation in vascular malformations, it is assumed that H19 has an indirect effect on KRAS upregulation." (PMID 34489556, 2022). "We therefore wanted to examine the impact of downregulated H19 expression on the anti‐tumour effects of resveratrol." (PMID 35166018, 2022). "LncRNA-H19 can regulate various biological processes via the H19/miR-675 axis by targeting oncogenic or tumor suppressive factors because miR-675 has numerous targets in various signaling pathways." (PMID 36671388, 2022). "The mRNA expression of H19 was higher in EBV-positive tumor cells treated with 5-Aza-CdR (15 μmol/L) for 3 days compared with EBV-positive tumor cells treated with DMSO." (PMID 35674441, 2022). "In various types of cancers, long non-coding RNA H19 (lncRNA H19) has been shown to play critical roles in tumor development, proliferation, metastasis, and multiple drug resistance as well." (PMID 36246634, 2022). "The H19 lncRNA was suggested to be involved in the maintenance of the right proportion of oncogenic to tumor-suppressing lncRNAs in a vitamin D3/VDR signaling-dependent manner." (PMID 35328609, 2022). "Noticeably, abnormal expression of lncRNA H19 has been found in different types of tumor cells, affecting cancer progression through different mechanisms, either as a suppressor or oncogenic gene, depending on cellular context." (PMID 35955440, 2022). "H19 sustains tumor growth and bortezomib resistance by inhibiting the tumor suppressor miR-29b-3p and by increasing the levels of the anti-apoptotic protein MCL-1." (PMID 35454868, 2022). "LncRNA H19 has been confirmed to be involved in many biological processes in various tumors, such as tumor cell proliferation, invasion and apoptosis." (PMID 35506202, 2022). "Specifically, oncogenic lncRNAs frequently associated with cancer metastasis, such as H19, LINC01134 were significantly reduced in MS-1 cells by MeSG treatment, indicating the potential importance of lncRNA expression in MCC tumor progression." (PMID 36146655, 2022). "In vivo, sulforaphane- or H19 or APOBEC3G siRNAs led to significantly smaller tumor xenografts with reduced expression of Ki67, APOBEC3G and phospho-Smad2." (PMID 33669381, 2021). "Its upregulation is associated with the progression of HCC, and the expression of lncRNA H19 is correlated with tumor stage, distant metastasis and poor prognosis of HBV-related HCC." (PMID 34869051, 2021). "Further investigations showed that H19 overexpression inhibited proliferation and colony formation in vitro, and reduced xenografts tumor burden in vivo." (PMID 34484116, 2021). "In-vivo therapeutic applications: H19 promoted proliferation, migration, and angiogenesis in tumor xenograft investigations, while its knockdown inhibited tumor progression." (PMID 34322395, 2021). "LncRNA H19 can act either as an oncogene or a tumor suppressor gene, and is reported to play an important role in the occurrence, development, invasion, and metastasis of various tumors, and can also serve as a biomarker of cancer prognosis." (PMID 33881140, 2021). "A meta-analysis showed that dysregulated H19 expression correlated with poor differentiation, high tumor stage, early distant metastasis, and lymph node involvement in multiple cancers." (PMID 34527584, 2021). "The high expression of H19 is positively correlated with advanced tumor-node-metastasis (TNM) stage and tumor size." (PMID 33422081, 2021). "The data showed that exosomal H19 administration not only reduced tumor growth in PitNET xenografts, but increased sensitivity to cabergoline, a common therapeutic for lactotroph PitNETs." (PMID 33808624, 2021).
tumor (continued). "Cell 3 and its primary tumor 3 presented 28 genomic alterations in common, including gains of 4q12 (PDGFRA), an amplification of 11p15.5 (H19 and IGF2 genes), and a loss of 6p25.3 (DUSP22)." (PMID 33917394, 2021). "After treatment with GEM, the survival rate of CCA cells QBC939 and the weight of the tumor were significantly lower in H19 high expression group; the findings suggested that high expression of H19 can increase the sensitivity of CCA cells to GEM." (PMID 33402118, 2021). "The lncRNA H19, firstly described as an onco-fetal transcript, exhibits higher expression in both tumor samples and thyroid cancer cell lines." (PMID 33030666, 2021). "H19 is now widely believed to be an oncogene that contributes to tumor initiation and progression for many cancers including HCC." (PMID 33445757, 2021). "The earliest known tumor-related lncRNAs, such as H19 which were found to promote tumor-related angiogenesis, inhibit tumor cell apoptosis, and increase the proliferation and hypoxia tolerance of tumor cells." (PMID 34079084, 2021). "The results showed that the expression of H19 was negatively correlated with tumor purity and B-cell invasion, which was statistically significant (p < 0.05)." (PMID 34922547, 2021). "hnRNPA2B1‐dependent H19 has been reported to be contained in exosomes, with a capacity to transfer gefitinib resistance to tumor cells." (PMID 33931980, 2021). "The cancer-associated fibroblasts-derived exosomes were shown to carry lncRNA H19, which is highly expressed in tumor stroma in comparison to tumor tissue." (PMID 34680193, 2021). "Studies have found that the high expression of lncRNA H19 is closely related to the proliferation, differentiation, and metastasis of tumor cells, and the expression of lncRNA H19 is significantly correlated with the severity of tumor invasion." (PMID 34794451, 2021). "In GBC, H19 expression has been shown to be overexpressed in tumor tissue than in adjacent non-tumor tissue." (PMID 34575316, 2021). "H19 has been investigated for years, and several studies have suggested that H19 possesses both oncogenic and tumor-suppressive effects (see reviews)." (PMID 33672311, 2021). "The DTA-19 targeted by H19 has also shown promising prospects in anti-cancer therapy by suppressing tumor growth after intratumoral injection." (PMID 33402118, 2021). "DTA-19 is a double-stranded DNA plasmid containing H19 regulatory sequence; it targets the highly expressed H19 in tumor cells to specifically kill cancer cells." (PMID 33402118, 2021). "H19 opposite tumor suppressor (HOTS) inhibits cell growth in a cervical cancer cell line, whereas its silencing promotes cell growth in vitro and tumorigenicity in vivo, indicating that it is an imprinted tumor suppressor." (PMID 34069428, 2021). "Previous studies also indicated that lncRNA H19 regulated tumor carcinogenesis, angiogenesis, and metastasis." (PMID 33716779, 2021). "The C2C12 H19- cell lineage showed alterations similar to cancer cells, suggesting an important role of H19 in the cancer initiation process as a tumor suppressor gene." (PMID 34526543, 2021). "H19 competes with miR-141 and activates the β-catenin pathway, maintaining tumor cell stemness and promoting drug resistance." (PMID 34067896, 2021). "The function of H19 in cancer development is intricate, as it can be tumor-suppressor or pro-oncogenic, depending on cellular context of H19 and tumor types." (PMID 34440876, 2021). "ARF promotes EMT and cell migration of tumor cells; H19 critically contributes to a change in ARF abundance by sponging its regulators." (PMID 35011635, 2021). "Our findings suggest that the presence of LncRNA H19 SNP rs217727 is related to the EGFR mutation in LADC patients, and the LncRNA H19 SNP rs217727 and rs2107425 are associated with progressed tumor status for LADC patients with EGFR wild-type." (PMID 33799753, 2021).
tumor (continued). "Combined with our data from the tumor stroma, lncRNA H19 was identified as a seed prediction of EMCTs and a key lncRNA in oral CAFs." (PMID 33762576, 2021). "In CC, there is an abnormal expression of H19 where it plays an important role in tumor development." (PMID 34204445, 2021). "In the current study, nevertheless, the correlation of LncRNA H19 SNP rs217727 and rs2107425 to the tumor progression of LADC with EGFR wild-type has been observed which is a preliminary experience for this field." (PMID 33799753, 2021). "Modulating the miR-342/Wnt5a/β-catenin axis is one of the proposed mechanisms for the oncogenic effect of H19 on tumor growth, metastasis, and angiogenesis in vivo." (PMID 34322395, 2021). "Administration of a plasmid (BC-819) carrying the gene for diphtheria toxin under the regulation of the H19 gene promoter was utilized to investigate its anti-tumor responses in various solid tumors." (PMID 34771549, 2021). "For instance, H19 can exhibit proto‐oncogene activities that promote tumour development and growth, but can act as a tumour suppressor gene in other tumours by inhibiting tumour proliferation, metastasis and invasion." (PMID 33236528, 2021). "The direction of the common gene expression changes, i.e. activation or repression, was concordant in both tumour groups, with the exception of long non-coding RNA H19, which was repressed in GE1-HCC and increased in GE2-HCC." (PMID 33541355, 2021). "In vitro and in vivo data showed that H19 overexpression promoted tumor growth and metastasis and revealed that H19 activated PI3K/AKT/CREB signaling and promoted pNEN progression by interacting with VGF (VGF nerve growth factor inducible)." (PMID 34576322, 2021). "Our previous studies showed that low doses of metformin can downregulate the expression of long noncoding RNA H19, thereby inhibiting the metastasis of tumor cells." (PMID 34162423, 2021). "The authors performed further in vitro and in vivo studies revealing H19 overexpression significantly reduced tumor growth." (PMID 33808624, 2021). "Runt domain transcription Factor 1 (RUNX1), an important tumor suppressor, is an important downstream molecule of the H19/miR-675 axis, and both H19 and miR-675 decrease RUNX1 expression." (PMID 34977037, 2021). "The long noncoding RNA (lncRNA) H19 represents tumor-promoting or tumor-suppressive actions and is regulated under inflammatory conditions." (PMID 34948424, 2021). "The tumor volumes in the Cal-27 + CAFs group were larger than those in the controls, and lncRNA H19 knockdown exhibited a suppressive role in tumor growth." (PMID 33762576, 2021). "H19 upregulation, evaluated by qRT-PCR reduces tumor progression and cell proliferation by inhibiting the mTORC1 normal function that mediates 4E-BP1 phosphorylation." (PMID 34885097, 2021). "Several studies have shown that H19 is related to the development of cancer, and the H19 locus can show tumor-suppressive effects in some cancers." (PMID 33478579, 2021). "The downregulation of the tumor promoter H19 and its target gene APOBEC3G was most significant and converged in inhibition of Smad2/TGF-β, which is involved in prevention of PDAC progression." (PMID 33669381, 2021). "We confirmed the in vitro data by performing the tumorigenesis experiment in nude mice and found that overexpression H19 promoted tumor growth while PI3K inhibition restricted tumor growth." (PMID 34250088, 2021). "Other studies have identified H19 as either an oncogene or tumor suppressor, depending on tumor type 121-125." (PMID 32368311, 2020). "The mechanism is that the direct binding of H19 to miR-141 activates the Wnt/β-catenin signaling pathway in tumor cells." (PMID 33520725, 2020).
tumor (continued). "H19, one of the first identified lncRNAs in the early 1990s, was found to be involved in a tumor development promotion, being activated by oncogenic pathways such as PI3K/AKT, acting by sponging notable tumor suppressive miRNAs, for example let-7." (PMID 32545208, 2020). "It has also been reported to have high levels of circulating H19 in GC patients, being inversely related to tumor size." (PMID 33519750, 2020). "The four main molecular subtypes of BWS (KCNQ1OT1:TSS-DMR-LOM, H19/IGF2:IG-DMR -GOM, UPD, and CDKN1C mutations) are characterized by specific genotype-phenotype correlation to tumor development risk." (PMID 33101381, 2020). "Targeting H19 lncRNA using shRNA reduces H19 expression level in vivo, which subsequently resulted in a strong reduction of tumour burden and inhibition of metastases in an orthotopic ATC mouse model." (PMID 33126409, 2020). "SNORA7A restoration impairs H19-mediated osteogenesis and tumor suppression, indicating an oncogenic role of SNORA7A." (PMID 33519915, 2020). "Higher levels of H19 were significantly associated with advanced TNM stage (p=0.012), primary tumor (p=0.015), and lymph nodes (p=0.018)." (PMID 32742441, 2020). "H19 was supposed to be one of the top overexpressed lncRNA both in primary tumor and metastatic tissues compared with adjacent normal tissues." (PMID 32698890, 2020). "RNA fluorescence in situ hybridization revealed that H19 was predominantly expressed in tumor stroma, and CAFs expressed higher levels of H19 than normal fibroblasts." (PMID 33050576, 2020). "In the iPSA < 7 ng/mL group, the H19 mRNA level was significantly lower in patients in advanced tumor stages than in those in the T2 stage (p = 0.042)." (PMID 32878251, 2020). "H19 was described to work either as a tumor suppressor in vitro and in vivo, or to have oncogenic features." (PMID 32429417, 2020). "On the other hand, in vivo mouse and LFS iPSC-derived osteoblast studies demonstrated that H19 displays a tumor-suppressive effect." (PMID 33519915, 2020). "Our current study reveals that H19 functions as a tumor suppressor through negatively regulating the expression of oncogenic SNORA7A in the osteoblast context." (PMID 33519915, 2020). "Evidences have shown that H19 can function either as a tumor suppressor or as a tumor promoter, depending on the type, stage, and genetic background of cancer cells." (PMID 32760219, 2020). "A decrescent small tumour was revealed in the combined treatment of shH19 and Gefitinib compared with down‐regulation of H19 or Gefitinib treatment alone." (PMID 32281297, 2020). "Conclusions from studies in the literature range from H19 being a tumor suppressor to H19 being an oncogene in HCC." (PMID 32429417, 2020). "One study finds that NSCLC cells exposed to gefitinib increases the expression of H19, which is delivered to other cells through exosomes secreted by primary tumor." (PMID 33072553, 2020). "We found that the H19 mRNA expression was significantly lower in patients with an advanced tumor stage when they had iPSA of ≤ 7 ng/mL in the TCGA database." (PMID 32878251, 2020). "Considering of CRISPR/Cas9 system is highly efficient for gene editing 20; thus, the effect of H19 knock out (KO) on tumor development was also evaluated in vivo in nude mice." (PMID 32485786, 2020). "H19 not only is a tumor suppressor but also can promote the proliferation and migration of cancer cells." (PMID 33204219, 2020). "Distant lung metastasis represents one of the most lethal threats of thyroid carcinomas and H19 has been proven to be engaged with lung metastasis in other tumour types." (PMID 33126409, 2020).
tumor (continued). "One study found that H19 plays a more complex role in tumorigenesis, both carcinogenic and tumor suppressive." (PMID 32596158, 2020). "Together, these results demonstrate that the PIM kinases control the level of lncRNA H19, which in turn modifies stem cell gene transcription regulating tumor growth." (PMID 32146726, 2020). "The results demonstrated that inhibited tumor growth was observed after injected H19 KO cells compared with control group." (PMID 32485786, 2020). "These tumor-promoting effects of H19 appear to be mediated through miR-675, miR-29a, miR-140, and miR-138/HIF-1α." (PMID 32650527, 2020). "In the present study, we found that down‐regulation of H19 inhibited the progression of tumour growth in the xenograft model compared with control group." (PMID 32281297, 2020). "Intriguingly, let-7a suppression significantly rescues the weakened tumor cell motility induced by sh-H19." (PMID 33123473, 2020). "This confirms our results of H19 as prognostic in intra cancer group with different levels of expression in the different tumor categories." (PMID 33335214, 2020). "The lncRNA H19 is a well-known tumor marker and negatively correlated with tumor progression in PitNET." (PMID 32498309, 2020). "H19-derived miR-675 favors the tumor progression by repressing several well-known tumor suppressor genes, such as Rb, Twist1 or RUNX1." (PMID 32610610, 2020). "LncRNAs can function either as oncogenes (e.g., HOTAIR, MALAT1, H19) or as tumor suppressors (e.g., HOTAIRM1, NKILA, XIST) by targeting genes that foster or prevent tumor development and progression, respectively." (PMID 33049922, 2020). "We confirmed that SNORA7A, a snoRNA known to promote MSC proliferation and self-renewal, is suppressed by H19 and that restoration of SNORA7A expression impaired H19-mediated osteogenesis and tumor suppression." (PMID 33519915, 2020). "Taken together, most in vivo studies support a tumor suppressor function for H19, with the exception of one xenograft model." (PMID 32429417, 2020). "Regarding BTC, several studies demonstrated an oncogenic role of H19 including its association with unfavorable clinical characteristics such as advanced TNM-stage, tumor size and bad prognosis." (PMID 32331331, 2020). "Combined with the proof of CSC regulation by H19, this highlights the importance of exosomal transportation of H19 within the tumor." (PMID 33291403, 2020). "The hypoxia microenvironment induces endogenous expression of H19 via Hif-1α, which directly binds to the H19 promoter, triggering the oncogenic effects in tumor cells." (PMID 32283739, 2020). "Small molecule pan‐PIM inhibitors (PIM‐i) currently in clinical trials reduced H19 expression in both of these tumor types." (PMID 32146726, 2020). "H19 closely correlates with the degree of tumor differentiation and promotes PC cell proliferation by modulating the expression of E2F-1, a direct target of H19-derived miR-675-5p 7,16." (PMID 32626524, 2020). "Upregulated H19 expression in CAPAN-1 cells promoted tumor cell migration, invasion, EMT and chemoresistance." (PMID 32626524, 2020). "Using an optimized streptavidin-binding RNA aptamer designed from H19 lncRNA, we revealed that H19-tethered protein complexes include proteins critical for DNA damage response and repair, confirming H19's tumor suppressor role." (PMID 33519915, 2020). "Further analysis in vivo demonstrated that overexpression of H19 leads to more metastases and larger tumor size in lung compared with control cells." (PMID 32698890, 2020). "In vivo experiments involving subcutaneous injection of K562 cells engineered with a stable knockdown of H19 into mice demonstrated the tumorigenic role of H19, since a significant decrease of tumor growth was observed." (PMID 33134177, 2020). "LncRNA H19 was highly expressed in tumor tissues and increased according to cancer development stages and metastasis status." (PMID 33050576, 2020).